MIS18A (MIS18 kinetochore protein A)
Description:
Required for recruitment of CENPA to centromeres and normal chromosome segregation during mitosis.
Synonyms: C21orf45; C21orf46; FASP1; B28; hMis18alpha; MIS18alpha
Tractability: PROTAC: UniProt records ubiquitination sites on it; ubiquitination databases record sites on it.
Gene: Protein-coding gene on chromosome 21 (32,268,224 to 32,279,098, reverse strand). Ensembl gene ENSG00000159055.
Subcellular location: Nucleus; Chromosome; Chromosome, centromere
Subcellular location (Human Protein Atlas): Cytosol; Nucleoplasm
Pathways (Reactome):
Cell Cycle: Deposition of new CENPA-containing nucleosomes at the centromere
Gene Ontology:
Molecular function: identical protein binding; protein binding; protein-macromolecule adaptor activity
Biological process: CENP-A containing chromatin assembly
Cellular component: CENP-A recruiting complex; chromatin; chromosome, centromeric region; nucleoplasm; nucleus; chromosome
Genetic constraint (gnomAD): Loss-of-function variants: 12 observed, 14.14 expected, observed/expected ratio (o/e) 0.85, 90% interval 0.54 to 1.37. The upper end of that interval is the gene's LOEUF score, 1.37, which puts it in group 5 of 6, group 1 being the genes least tolerant of losing a copy. Missense variants: 230 observed, 195.66 expected, observed/expected ratio (o/e) 1.18, 90% interval 1.05 to 1.31. Synonymous variants: 102 observed, 84.96 expected, observed/expected ratio (o/e) 1.2, 90% interval 1.02 to 1.41.
Homologues: Orthologues: chimpanzee MIS18A (99% identical), macaque MIS18A (95% identical), pig MIS18A (81% identical), dog MIS18A (79% identical), rabbit MIS18A (75% identical), rat Mis18a (70% identical), guinea pig MIS18A (67% identical), mouse Mis18a (67% identical), tropical clawed frog mis18a (33% identical), zebrafish mis18a (27% identical). Paralogues in human: OIP5 (18% identical).
Diseases named in the same sentence as MIS18A in open-access papers:
MIS18A is named in the same sentence as 6 diseases in open-access papers, as found by Europe PMC text mining. Sharing a sentence is not in itself a finding about the gene and the disease. The quoted sentences say what the papers report.
tumor (4 papers, 2013 to 2024). "The top five differential genes in LumB tumours, ranked by significance, are MIS18A, WIF1, CHEK2, EMCN and CDK4." (PMID 38332687, 2024).
infection (1 paper, 2018). The state of being infected such as from the introduction of a foreign agent such as serum, vaccine, antigenic substance or organism. "The infection of cells with lentivirus reduced the level of endogenous Mis18α efficiently." (PMID 29416714, 2018).
MIS18A also shares sentences with these, for which no sentence is quoted: cancer (1 paper); carcinoma of the gall bladder (1); hematological malignancies (1); Obesity (1).